DGAT1 (diacylglycerol O-acyltransferase 1)
Diseases named in the same sentence as DGAT1 in open-access papers (continued):
Sharing a sentence is not in itself a finding about the gene and the disease.
steatosis (25 papers, 2015 to 2025). Increased lipid within the cytoplasm of cells. "DGAT1 deficient murine primary hepatocytes are indeed protected from steatosis by decreased lipogenesis and increased beta-oxidation rates." (PMID 27428418, 2016). "The effect of MALAT1 silencing on DGAT1 expression in the presence of Ex-4 suggests that Ex-4 reduces OA-induced steatosis by a mechanism that implicates the deactivation of DGAT1, and, thus, TG synthesis, via the modulation of MALAT1." (PMID 40002783, 2025). "Selective overexpression of DGAT1 (a key gene in lipogenesis) in cardiomyocytes induces cardiac steatosis and fibrosis 52, exacerbating angiotensin II-induced heart failure in mice." (PMID 40166006, 2025). "Sleeve gastrectomy did not change BAT weight, but improved BAT morphology and function, as shown by the reduction in brown adipocyte hypertrophy and steatosis, together with the repression of the transcription of the lipogenic genes Pparg2, Mogat2 and Dgat1." (PMID 36834823, 2023). "Both uroguanylin and guanylin downregulated basal and palmitate-induced transcription of Srebf1 and Dgat1 as well as steatosis in RIN-5mF β-cells (all P<0.05)." (PMID 37274331, 2023). "DIO promoted BAT whitening, evidenced by increased BAT hypertrophy, steatosis and upregulation of the lipogenic factors Pparg2, Mogat2 and Dgat1." (PMID 36834823, 2023). "To summarize, our results indicate that in steatosis the hepatic expression of DGAT-1, DGAT-2, FASN, and SREBP-1 increased significantly, and this increase was counteracted by the treatment with the nutraceutical formulation." (PMID 36135761, 2022). "Moreover, global and liver-specific inactivation of DGAT1 in mice afforded protection from steatosis due to a high-fat diet." (PMID 40002783, 2025). "Importantly, both guanylin and uroguanylin decreased basal and palmitate-induced steatosis and downregulated factors involved in lipogenesis (Srebf1, Mogat2 and Dgat1)." (PMID 37274331, 2023). "Additionally, we noted only a very modest steatosis-reducing effect of DGAT1 inhibition in both genetic and FFA models, contrasting the effects of DGAT2i." (PMID 36823355, 2023). "As a result, the low DGAT1 expression observed in the presence of Ex-4 is most likely a response to reduced FAs uptake rather than reduced de novo lipogenesis, ruling out a role for reduced de novo lipogenesis in the Ex-4-induced steatosis improvement." (PMID 35140289, 2022). "Examination of molecular pathways by which deletion of ghrelin reduces steatosis showed that the increase in expression of diacylglycerol O‐acyltransferase‐1 (DGAT1), one of the key enzymes of triglyceride (TG) synthesis, seen with age in WT mice, is not present in KO mice." (PMID 29024407, 2018). "Accordingly, sleeve-gastrectomized rats exhibited a tendency towards a downregulation in hepatic Pparg (P = 0.084) and Srebf1 (P = 0.153) transcription factors as well as lower (P < 0.05) mRNA levels of Mogat2 and Dgat1 and mild steatosis evidenced by adipophilin staining." (PMID 28008992, 2016). "On the other hand, emodin has also been noted to decrease DGAT-1 content within in vitro models of steatosis hepatic L02 cell in addition to reports highlighting water extracts of Radix Polygoni multiflori can decrease hepatic DGAT activity in high fat diet-fed rats." (PMID 26031670, 2015). "Yet during lipodystrophy, increased de novo hepatic fatty acid synthesis caused steatosis, independent of changes in DGAT1, suggesting that static changes in DGAT1 may not have a significant contribution to TAG synthesis." (PMID 34327606, 2022). "Combined DGAT1 and DGAT2 inhibition provided a synergistic effect that completely reverted the steatosis phenotypes of both genetic and FFA-induced steatosis models, already evident at nanomolar concentrations." (PMID 36823355, 2023). "ANGPTL8 reduced the steatosis (p < 0.05) and mRNA expression levels of PPARG2, SREBF1, MOGAT2 and DGAT1 lipogenic genes of palmitate-treated hepatocytes." (PMID 34884755, 2021).
steatosis (continued). "Interestingly, ANGPTL8 inhibited steatosis and expression of lipogenic factors (PPARG2, SREBF1, MOGAT2 and DGAT1) in palmitate-treated human hepatocytes." (PMID 34884755, 2021). "This is consistent with the previous observations that, in the absence of DGAT1, steatosis from preformed FAs is much diminished, presumably because this would require the activity of overt (cytosol-facing) DGAT1." (PMID 30397187, 2019). "HCV core protein within the cell accumulates in a globular pattern around the lipid droplets by means of interaction with DGAT1, and DGAT1−/− mice do not develop steatosis induced by HCV core protein." (PMID 31319842, 2019). "However, Dgat1 expression was also decreased in the high-fat diet group, which together with the reduced Mttp expression, showed that steatosis in our animal model was characterized neither by triglyceride production nor by their excretion from the liver." (PMID 41262214, 2025).
glioblastoma (19 papers, 2021 to 2025). The most malignant astrocytic tumor (WHO grade IV). "More recently, DGAT1 has been linked to reducing oxidative stress and lipotoxicity in glioblastoma and melanoma." (PMID 37268606, 2023). "DGAT1 protects glioblastoma cells from damage caused by excessive FAO by converting excess fatty acids into triglycerides." (PMID 36588702, 2022). "Inhibition of DGAT1 in multiple glioblastoma cell lines and patient-derived GBM30 cells in vitro caused dysregulated lipid metabolism, triggering the accumulation of acylcarnitines and the production of ROS, resulting in apoptosis." (PMID 34983949, 2022). "High levels of DGAT1 are associated with poor survival in patients with glioblastoma." (PMID 34503201, 2021). "Compared to normal brain tissue, DGAT1 is upregulated in glioblastoma tissues, and high DGAT1 expression is correlated with poor prognosis." (PMID 40097417, 2025). "In conclusion, inhibitors of SOAT1 and DGAT1 show promising efficacy in reducing LDs accumulation in glioblastoma cells." (PMID 40097417, 2025). "While DGAT1 inhibition suppresses tumor growth in various cancers, including glioblastoma, melanoma, and prostate cancer, overexpression of DGAT2 inhibits cell proliferation in hepatocellular carcinoma (HCC)." (PMID 41041279, 2025). "DGAT1 inhibition restricts lipid metabolism, leading to increased ROS release in glioblastoma, and subsequent suppression of tumor growth." (PMID 40554491, 2025). "For example, ionizing radiation increased DGAT1 expression in glioblastoma, genetic inhibition of DGAT1 suppresses radioresistance and enhanced radiosensitivity of U87MG and U87MG-RR cells." (PMID 40554491, 2025). "DGAT1 has been reported to be a therapeutic target in glioblastoma, and blocking DGAT1 in glioblastoma models has been found to prevent lipid droplet formation, initiate cell death in tumors, and notably decrease tumor growth." (PMID 39728504, 2024). "The signficance of DGAT1 up-regulation and subsequent formation of LD to cancer has recently been demonstrated in glioblastoma models, in which DGAT1 inhibition led to tumor cell death through induction of lipotoxicity and oxidative stress." (PMID 35732120, 2022). "The inhibition of DGAT1 has proven especially effective in preventing TAG synthesis in various patient-derived IDHwt glioblastoma cell lines." (PMID 36012521, 2022). "The ability of DGAT1 inhibitor alone to suppress tumor growth was recently shown in a glioblastoma xenograft model." (PMID 35732120, 2022). "DGAT2, a functionally related albeit structurally distinct enzyme, appeared less important than DGAT1 for melanoma LD formation, cell growth, and survival, as was shown previously to be the case for glioblastoma cells." (PMID 35732120, 2022). "Inhibition of DGAT1 by A922500 effectively prevents the conversion of fatty acids to triglycerides and ultimately inhibits glioblastoma." (PMID 36588702, 2022). "DGAT1 is responsible for the synthesis of TAGs and is highly expressed in glioblastoma patient tissues, which correlates with poor patient survival." (PMID 34983949, 2022). "One study demonstrated that DGAT1 in glioblastoma cells is capable of protecting tumors from lipotoxicity, labeling it as a potential metabolic target for cancer therapy." (PMID 34581907, 2021). "Inhibiting DGAT1 by A-922500 alters lipid homeostasis and increases acylcarnitine levels, inducing mitochondrial damage and oxidative stress, and triggering apoptosis in glioblastoma cells." (PMID 40097417, 2025). "Moreover, DGAT1 protects glioblastoma (GBM) cells against oxidative stress and regulates lipid levels by storing excess FAs." (PMID 39728504, 2024). "DGAT1, a key protein in lipid accumulation, promoting LDs formation and protecting cancer against lipid peroxidation, has been found to play indispensable oncogenic roles in melanoma and glioblastoma." (PMID 37700339, 2023). "In the glioblastoma tumor, the expression of DGAT1 is higher compared to healthy brain tissue." (PMID 37046844, 2023).
glioblastoma (continued). "The expression of DGAT1 in the glioblastoma tumor is much higher than that of DGAT2." (PMID 37046844, 2023). "Additionally, treating IDHwt glioblastoma xenograft mouse models with another DGAT1 inhibitor, A-922500, induces apoptosis and significantly reduces the tumor size." (PMID 36012521, 2022). "In contrast, DGAT1 inhibition was recently reported to drive fatty acid-dependent oxidation in mitochondria generating high levels of reactive oxygen species, leading to apoptosis and significant growth inhibitory effects in glioblastoma." (PMID 36591531, 2022). "It has been shown that DGAT1 prevents lipotoxicity in glioblastoma by promoting LD storage of FAs." (PMID 34503201, 2021). "Glioblastoma cells store excess FAs into triglycerides and lipid droplets (LDs) by upregulating diacylglycerol-acyltransferase 1 (DGAT1), and inhibition of DGAT1 promotes glioblastoma cell death through excessive FAO-mediated reactive oxidative species (ROS) production." (PMID 33530546, 2021). "Studies have shown that glioblastoma (GBM) up-regulates DGAT1, which stores excess fatty acids as triglycerides and lipid droplets." (PMID 40002387, 2025). "The expression of DGAT1 in glioblastomas (GBM) tissues was significantly higher than that of DGAT2, and the expression of DGAT1 in poorly differentiated tumor tissues was higher than that in well-differentiated tumor tissues." (PMID 38500157, 2024). "Besides, DGAT1 was first reported in 2020 as a novel target for glioblastoma." (PMID 36588702, 2022). "Conversely, antagonism or depletion of DGAT1 in melanoma cell lines over-expressing endogenous DGAT1 led to a reduction in the amount of LD beginning between 12 and 24 h and continuing until 72 h, as previously reported for glioblastoma cells and other cell types." (PMID 35732120, 2022). "Indeed, genetic inhibition of DGAT1 in vivo suppresses tumor growth and prolongs the survival of glioblastoma-bearing mice, demonstrating that targeting DGAT1 may offer therapeutic benefit for patients with glioblastoma." (PMID 34983949, 2022). "Furthermore, higher expression of DGAT1 in glioblastoma may be associated with worse prognosis for glioblastoma patients, although GEPIA does not associate the expression of DGAT1 or DGAT2 with prognosis in glioblastoma patients." (PMID 37046844, 2023). "Elevated DGAT1 expression, but not DGAT2, is associated with poorer overall survival among glioblastoma patients." (PMID 40097417, 2025). "Moreover, an even higher dose of A922500 (47 μM) was unable to suppress LD dependent on DGAT2 or to markedly suppress viability in glioblastoma cells over-expressing DGAT2, consistent with A922500 being a selective DGAT1 inhibitor at this concentration." (PMID 35732120, 2022).
prostate carcinoma (17 papers, 2017 to 2026). A carcinoma that arises from epithelial cells of the prostate gland. "DGAT1 encodes a key enzyme in lipogenesis, which was found increased in prostate cancer cells and could facilitate cell proliferation and migration." (PMID 32732980, 2020). "Targeting DGAT1 disrupts lipid-mediated cancer-stroma interactions, offering a new therapeutic strategy to reduce aggressive prostate cancer in AA men." (PMID 42118850, 2026). "Collectively, these findings reveal that DGAT1 is a pivotal enzymatic regulator of fibroblast activation and lipid-driven remodeling in the prostate cancer tumor microenvironment of AA men." (PMID 42118850, 2026). "Another study reported a positive correlation between DGAT1 and the LD pool in prostate cancer in vitro, and that DGAT1 knockdown suppresses colony formation." (PMID 40083687, 2025). "Targeting LD biogenesis using DGAT1 inhibitor has been proposed in combination with chemotherapy to increase cell death in prostate cancer or to promote ferroptosis during tumor acidosis." (PMID 40560062, 2025). "In prostate cancer cells, the knockdown of DGAT1 leads to decreased cell growth and increased autophagy, suggesting a potential therapeutic target." (PMID 41041279, 2025). "Previous studies have shown that targeting DGAT1 in GBM or prostate cancer can impair FA metabolism and thus induce mitochondrial damage, excessive ROS production, and ultimately apoptosis through a blockade of the autophagy flux." (PMID 39667305, 2024). "DGAT1, a gene known to promote tumor progression in ovarian and prostate cancer, was found to promote the proliferation and migration of breast cancer cells." (PMID 37644433, 2023). "EPHB2 acts as EPHB2, a suppressor of prostate cancer cells, is able to exert its tumor suppressive effect by inhibiting the activity of lipogenic factors DGAT1, DGAT2 and promoting the lipolytic factor ATGL, PEDF." (PMID 35912266, 2022). "DGAT1, ABHD5, and ATGL are overexpressed in prostate cancer cells compared to peripheral blood mononuclear cells, and inhibition of DGAT1 and ABHD5 was found to lead to prostate cancer cell death." (PMID 35912266, 2022). "We recently showed that pharmacological inhibition of DGAT1 in breast and prostate cancer cells blunted TG synthesis and influenced cell viability." (PMID 33413672, 2021). "We postulated that, in prostate cancer (PCa) cells, augmented lipogenesis and growth are due to increased DGAT1 expression leading to microtubule-organizing center (MTOC) amplification." (PMID 30816200, 2019). "In the present study, we show that DGAT1 is overexpressed in prostate cancer (PCa) cells compared to normal prostate epithelium, and that the inhibition of this lipogenic enzyme can reduce not only LD density, but also the ncMTOC number and MT stability." (PMID 30816200, 2019). "This study highlights DGAT1 as a promising multifunctional target to suppress growth and progression in prostate cancer." (PMID 30816200, 2019). "Our results indicate that DGAT1, ABHD5, ACAT1 and ATGL are overexpressed in prostate cancer cells compared to PBMCs and of these overexpressed genes, DGAT1 and ABHD5 aid in the growth of the prostate cancer cells." (PMID 28877685, 2017). "Our results indicate that four enzymes ACAT, ATGL ABHD5 and DGAT1 are differentially overexpressed in prostate cancer cells as compared to PBMCs." (PMID 28877685, 2017). "Utilizing these available small molecule DGAT1 inhibitors in future studies will help assess their therapeutic feasibility in prostate cancer." (PMID 28877685, 2017). "Since we observed maximum inhibition of growth with ABHD5 and DGAT1 siRNA we examined the mechanism by which these two genes promote prostate cancer growth." (PMID 28877685, 2017). "Ectopic DGAT1 expression in benign fibroblasts induced CAF markers' (FAP1 and αSMA) expression linked to fibroblast activation, altered the secretome, and significantly enhanced prostate cancer cells' growth in vivo." (PMID 42118850, 2026).
prostate carcinoma (continued). "Inhibition of DGAT1 decreased LDs density and affected the migration of prostate cancer cells." (PMID 39875372, 2025). "Recent studies confirmed that DGAT1-deficient cells were sensitized to lipid stress, resulting in increased caspase 3 and 7 activation, and knock-down of DGAT1 by siRNA decreased LD formation, resulting in autophagy and inhibited cell growth in prostate cancer LNCaP cells." (PMID 38786008, 2024). "It has been proven that DGAT1 could promote tumor progression in several cancer types, such as ovarian and prostate cancer, but the role of DGAT1 in BC is rarely studied." (PMID 34976839, 2021). "Data from several studies suggest that suppressed DGAT1 is a promising strategy to inhibit prostate cancer cell growth and, therefore, targeting DGAT1 might be conducive for clinical gastric cancer treatment." (PMID 33750350, 2021). "Likewise, knockdown of DGAT1 reduced lipid droplet number and cell proliferation and invasion of prostate cancer cells and glioblastoma." (PMID 33413672, 2021). "When compared to NHPrE, PC-3 cells showed a 3–4 fold higher levels of both ATGL (PC-3 vs NHPrE: 136.6 ± 1.6 vs 35.6 ± 1.6; P < 0.001) and DGAT1 (PC-3 vs NHPrE: 165.6 ± 1.5 vs 57.5 ± 1.6; P < 0.001), indicating that in prostate cancer cells both lipolysis and lipogenesis are highly active." (PMID 30816200, 2019). "Inhibition of either DGAT1 or ABHD5 leads to prostate cancer cell death." (PMID 28877685, 2017). "Our results strongly suggest that inhibition of both DGAT1 and ABHD5 promote prostate cancer cell death." (PMID 28877685, 2017). "In summary our findings indicate that inhibition of both DGAT1 and ABHD5 using siRNA leads to reduction in prostate cancer cell growth." (PMID 28877685, 2017). "As prostate cancer cells overexpress DGAT1 and ABHD5; both can be targeted to block prostate cancer cell growth." (PMID 28877685, 2017). "Both DGAT1 and ABHD5 can be selectively targeted to block prostate cancer cell growth." (PMID 28877685, 2017). "Palmitate induced apoptosis in PC-3 prostate cancer cells and MDA-MB-231 breast cancer cells was prevented by pre-treatment of these cells with FAs (oleate or oleate:palmitate:linoleate mix), and this protective effect required DGAT-1–mediated triacylglycerol synthesis." (PMID 33413672, 2021). "Interestingly, DGAT-1 is involved in the synthesis of triacylglycerol where as ABHD5 is a hydrolase and participates in the fatty acid oxidation process, yet inhibition of both enzymes similarly promotes prostate cancer cell death." (PMID 28877685, 2017).